NCF1 (neutrophil cytosolic factor 1)
Diseases named in the same sentence as NCF1 in open-access papers (continued):
Sharing a sentence is not in itself a finding about the gene and the disease.
Arthritis (continued). "Therefore, the B10.DR4.Ncf1*/* is a more arthritis-susceptible DR4-expressing CIA model and individuals from this strain were used for the experiments presented in the current study." (PMID 23116329, 2012). "Interestingly, the pristane-induced arthritis model used to identify the polymorphism in Ncf1 in rats is B-cell independent." (PMID 17897462, 2007). "Indeed, NCF1 has been identified as a gene that has a naturally occurring polymorphism regulating arthritis severity in rats." (PMID 15899035, 2005). "Thus, both Ncf1 and Fcgr2b deficiency contributed to the arthritis susceptibility." (PMID 35963953, 2022). "To study whether they could break T cell tolerance and allow the development of CIA driven by autoreactive T cells, we intercrossed Fcgr2b and Ncf1 deficient mice with the BQ.Col2266E strain and found that both genes could additively break the T cell tolerance and allow the development of arthritis." (PMID 35963953, 2022). "As the DA.Ncf1E3 congenic rats carry the arthritis-protecting variant of Ncf1, one might speculate that the effect caused by the functional Ncf1 is to generate a resistance to the effect from induction of Ass, Cxcl9 and Mmp12 genes, which might otherwise contribute to the development of arthritis." (PMID 17490473, 2007). "We have previously shown that ROS deficiency through mutations in the NCF1 protein, an essential component of the NOX2 complex in APCs, increases susceptibility to arthritis, systemic lupus erythematosus (SLE), and autoimmune encephalomyelitis." (PMID 38671946, 2024). "The results demonstrated that SOD3 reduced the severity of arthritis in Ncf1 (∗/∗) mice and wild-type mice, emphasizing the important role of SOD3 in relieving arthritis in mice." (PMID 37759978, 2023). "It was found that the adenovirus vector overexpressing SOD3 was directly injected into the paws of neutrophil cytosolic factor 1(Ncf1) (∗/∗) mice with collagen-induced arthritis." (PMID 37759978, 2023). "The arthritis of mCAIA in the BQ.Ncf1*/* mouse is a chronic and relapsing disease, which also includes a systemic inflammatory response and erosions of the affected joints." (PMID 35551534, 2022). "Collagen antibody induced arthritis was studied as a model of RA and mannan-induced psoriasis (MIP) was used as model for psoriasis and PsA, using mice with a mutation of Ncf1 on the B10.Q genetic background, making them highly disease susceptible." (PMID 35551269, 2022). "As both Fcgr2b and Ncf1 protected against the breach of T cell tolerance and development of arthritis, we next addressed the possibility that they operate in the same pathway, i.e., that they epistatically interact." (PMID 35963953, 2022). "The interaction between Fcgr2b and Ncf1 was additive, indicating that the pathways whereby they influence arthritis are mainly independent on each other." (PMID 35963953, 2022). "Compared to the wild type mCAIA mice, which recovered from arthritis and had blood neutrophils returning to normal levels at day 100, BQ.Ncf1*/* mCAIA had increased levels of blood neutrophils during the chronic phase." (PMID 35551534, 2022). "We find that Clec4b and Ncf1 exert an additive effect on arthritis given by their joint ability to regulate neutrophils." (PMID 35052516, 2021). "It has been shown that the mutated Ncf1, a gene encoded the p47 phox subunit of NOX2 complex, led to a more severe collagen-induced arthritis." (PMID 34557202, 2021). "We went on to try boosting PD-L1-PD-1 pathway to ameliorate the serum-induced arthritis by treating Ncf1-/- arthritic mice with recombinant PD-L1-Fc." (PMID 34557202, 2021). "Previous positional cloning identified Ncf1 and Clec4b to be major regulators of arthritis models in rats." (PMID 35052516, 2021). "We used congenic rats to investigate the interaction between the two most important arthritis-regulating genes in rats, Clec4b and Ncf1." (PMID 35052516, 2021).
Arthritis (continued). "In summary, the results of this study describe a novel role for Clec4b in mediating arthritis through the Ncf1/NOX2 axis which precipitates as an additive interaction on models of arthritis and ROS production." (PMID 35052516, 2021). "Positional cloning of PIA7 and PIA4 have identified Clec4b and Ncf1 as the regulating genes for arthritis severity and onset as well as controlling innate and adaptive immune responses." (PMID 35052516, 2021). "Fine mapping of both QTL led to the positional cloning of Clec4b (PIA7) and Ncf1 (PIA4) as the underlying polymorphic genes, which were found to regulate arthritis severity in multiple rat models (CIA and PIA)." (PMID 35052516, 2021). "The gene encodes a component of the NADPH oxidase complex and these studies catalyzed the development of a new therapy for arthritis, based on the use of oxidative-burst inducing substances (Arthritis, Ncf1 gene)." (PMID 32741357, 2020). "Examples of such models are collagen-induced arthritis or spontaneous arthritis in the SKG, K/BxN, or Ncf1 mutation mouse strains." (PMID 32448385, 2020). "Defective oxidative burst, due to a variation in the ncf1 gene, has been shown to result in an increased severity in T cell-dependent arthritis in animal models, an observation counteracted by a specific restoration of ROS production in macrophages." (PMID 32787920, 2020). "Our gene-disease association study supports the theory that NCF1 and NCF2 are associated with some immunological diseases including arthritis and granulomatous disease." (PMID 27878450, 2017). "Further studies using a Wistar congenic strain that differs from DA at only position 153 in Ncf1 conclusively showed that this position regulates ROS and mediates arthritis resistance in rats." (PMID 27736747, 2016). "As previously discussed, congenic strains have been used to show that the Ncf1 and APLEC polymorphisms contribute to not only arthritis but also EAE, and that Igl contributes to ovalbumin-induced airway inflammation." (PMID 27736747, 2016). "Other genes positionally identified from congenic studies, such as Ncf1 and APLEC, were newly linked to arthritis, and have been investigated for their roles in RA in humans." (PMID 27736747, 2016). "These congenic strains conclusively identified a minimal arthritis-protective interval of 300 kb that contained only two genes, Ncf1 and Gtf2i (general transcription factor IIi)." (PMID 27736747, 2016). "In COMP+/+Ncf1*/* mice, the incidence of arthritis was 80% with the day of disease onset at 36 to 38 days." (PMID 22906101, 2012). "Neutrophil cytosolic factor 1 (Ncf1), also known as p47phox, was one of the first single genes identified to regulate arthritis severity." (PMID 17490473, 2007). "Naturally occurring genetic polymorphisms in the Ncf-1 gene modulate the activity of the NADPH oxidase complex, which strongly regulates the severity of arthritis." (PMID 17490473, 2007). "We have recently shown that compounds inducing NCF1-dependent oxidative burst, e.g. phytol, have a strong ameliorating effect on arthritis in rats." (PMID 17490473, 2007). "For example, in QTL region Cia12, NCF1 has been shown by Olofsson and colleagues to be involved in the regulation of arthritis severity in rats." (PMID 15899035, 2005). "Therefore, we made new cross-breeding on the BQ.Col2266E or B10Q background inducing deficiency of both Fcgr2b and Ncf1 and immunized them with COL2 together with control groups, then recorded the development of arthritis." (PMID 35963953, 2022). "Here, we investigate epistasis between Ncf1 and Clec4b, two major regulators of arthritis in rats." (PMID 35052516, 2021). "Treatment with the NOS inhibitor, L-NAME, in the priming, rather than the effector, phase prevents Ncf1-mutated mice from developing CII-induced arthritis." (PMID 33717180, 2021).
Arthritis (continued). "The experiments with interaction between the Ncf1 and Clec4b alleles show that the effects are additive and promotes the arthritis along similar pathways but that do not interact epistatically." (PMID 35052516, 2021). "NCF-1 is a member of the NADPH (nicotinamide adenine dinucleotide phosphate, reduced form) oxidase complex, which was recently identified as a susceptibility gene for pristine-induced arthritis." (PMID 15987489, 2005). "However, in a recent study, treating Ncf1-mutated animals with the NOS inhibitor L-NAME during the priming phase rather than the effector phase inhibited CII-induced arthritis." (PMID 35740050, 2022). "Our observation that Ncf1-deficient mice are protected from IRBP peptide-induced EAU is difficult to reconcile with the findings of aggravated diseases detected in the same mice induced to develop two other models of autoimmune disorders, EAE induced by MOG and arthritis caused by collagen or serum." (PMID 32380695, 2020). "Importantly, the most strongly associated non-MHC gene Ncf1, which leads to increased arthritis severity with lower ROS response in the DA rat strain, is a genetic association that is clearly present also in human RA and systemic lupus erythematosus." (PMID 29118363, 2017). "This publication also described a polymorphism carried by C3H mice in the Ncf1 gene, but ruled out this candidate with a variety of studies, including the finding that B6 Ncf1−/− mice exhibited no increase in arthritis severity relative to wild type B6 controls." (PMID 24926442, 2014). "However, SNPs in less critical regions, like the 153 SNP in Ncf1 found in rat, apparently reduce but do not completely abolish ROS production, which leads to an increased susceptibility to arthritis." (PMID 17897462, 2007). "In fact, it was shown that a less functional Ncf1, and the resulting decrease in NADPH oxidase capacity to produce ROS, is a major cause of increased arthritis severity in both rat and mouse models of arthritis, an observation that challenges the general dogma of the inflammatory role of ROS." (PMID 17490473, 2007). "To compare the development of LPS-enhanced and mannan-enhanced arthritis, we injected Cab3 and anti-CII cocktail into BQ.Ncf1* mice." (PMID 32448385, 2020). "A polymorphism in the activating component of the nicotinamide adenine dinucleotide phosphate (NADPH) oxidase complex, neutrophil cytosolic factor 1 (NCF1), has previously been identified as a regulator of arthritis severity in mice and rats." (PMID 17490473, 2007). "BQ.Ncf1*/* mice, but not BQ mice, developed an early onset of severe arthritis with a high disease incidence followed by a chronic and relapsing disease course." (PMID 35551534, 2022). "Interestingly, the lack of NCF1-mediated ROS production did not alter collagenase-induced OA (CiOA) in arthritis or reduce cartilage damage." (PMID 35740050, 2022). "Variations in human NCF1, including copy number variations and SNPs, result in impaired immunity, as the enzyme is unable to function as an NADPH oxidase to trigger the oxidative burst in phagocytes, inducing autoimmune diseases such as arthritis, autoimmune lung disease, and lupus erythematosus." (PMID 36448060, 2022). "Mice without Ncf1 display augmented disease severity in two models of autoimmune disorders, experimental autoimmune encephalomyelitis (EAE) provoked by native myelin oligodendrocyte glycoprotein (MOG) and arthritis caused by collagen or serum." (PMID 32380695, 2020). "However, 24 adhesion molecules and chemokine/cytokine genes were identified, some of which are known to contribute to arthritis (e.g. CD44 and neutrophil cytosolic factor 1) and some of which are novel in this respect (e.g. CC chemokine ligand-27 and IL-13 receptor α1)." (PMID 15987489, 2005).
Arthritis (continued). "However, our previous research has shown that induced arthritis was not different between mCAIA induced in the RAG-deficient Ncf1*/* mice (with deficiency of the recombination activating gene, lacking B cells, αβ-T cells and natural killer T cells) and RAG-sufficient Ncf1*/* mice." (PMID 35551534, 2022).
Hypertension (39 papers, 2012 to 2026). The presence of chronic increased pressure in the systemic arterial system. "Studies of genotype–symptom interactions revealed that inclusion of the Ncf1 gene at the telomeric end of the WSCR into the deletion lowered patients' hypertension risk." (PMID 41292695, 2025). "Notable genes include ELN, coding for elastic fibers, in connection with connective tissue abnormalities and cardiovascular disease; and NCF1, in connection with the risk of hypertension." (PMID 37759207, 2023). "After a bioinformatic analysis of the quantitative trait locus peaks, Ren1, Ncf1, and Nos1 significantly emerge as modifiers to predispose to hypertension and stiffer blood vessels." (PMID 33086603, 2020). "Differences in the WBS deletion that affect the copy number for NCF1 finally affect hypertension risk on the severity of vascular stiffness." (PMID 33086603, 2020). "It has been reported that a functional NCF-1 gene increases the risk of hypertension in patients with WBS." (PMID 30319683, 2018). "It was observed that extension of the WBS deletion size to involve NCF1 gene was associated with protection from vascular stiffness and hypertension in WBS patients." (PMID 27525043, 2016). "Patients with ELN deletion and only one functional NCF1 allele have a 4-fold decreased risk of hypertension compared with those with more than one copy of NCF1." (PMID 22319452, 2012). "There is also evidence that NCF1 gene variants may contribute to hypertension by influencing ROS production in vascular cells." (PMID 40710296, 2025). "NCF1 gene dosage had been shown to modify the risk of hypertension in WBS patients." (PMID 22319452, 2012). "Reduced expression of NCF1 can limit the impact of ELN haploinsufficiency on hypertension by ameliorating the increase of ROS in the vascular walls through regulation of NOX1 and NOX2 NADPH oxidase complexes." (PMID 41292695, 2025). "The lower expression of NCF1 is related to lower blood pressure and minor ROS production, so if the deletion on chromosome 7 extends to include the NCF1 gene, the incidence of hypertension decreases." (PMID 36290706, 2022). "Contrastingly, hemizygosity for NCF1 generated lower oxidative stress, serving as a protective factor for hypertension." (PMID 34804071, 2021). "These combined studies indicate that both the Eln gene deletion and the Ncf1 gene presence contribute to observed murine hypertension." (PMID 22319454, 2012). "In WBS, the dosage of the NCF1 gene, encoding the p47phox subunit of NOX, is a strong modifier of the risk of hypertension." (PMID 22319452, 2012). "Deletion of a functional NCF1 gene copy has been shown to protect a proportion of WBS patients against hypertension, likely through reduced NADPH-oxidase (NOX)–mediated oxidative stress." (PMID 22319452, 2012). "Hypertension was significantly less prevalent in patients whose deletion included NCF1, indicating that hemizygosity for NCF1 was a protective factor against hypertension in WBS." (PMID 22319452, 2012). "While the previous studies focused on the role of P67phox or neutrophil cytosolic factor 2 (Ncf2) in the development of hypertension because it is located on chromosome 13, it is important to recognize that both P67phox and P47phox (Ncf1) play a critical role in the activation of ROS in macrophages." (PMID 33377622, 2021). "In addition to hypertension, Ncf1 plays an essential role in the development of diabetic nephropathy in the Akita mouse." (PMID 24025423, 2013). "Increased expressions of Ncf1 and Ncf2 have been described in several models of hypertension." (PMID 24025423, 2013). "However, the DD condition was reversed when the mice were mated with Ncf1+/− mice, indicating that the presence of the Ncf1 gene also contributes to the observed hypertension." (PMID 22319454, 2012).
Hypertension (continued). "We then crossed mice homozygous for a spontaneous loss of function mutation in Ncf1 with DD mice, in order to generate double heterozygotes in trans (DD/Ncf1−), resembling the genotype of WBS patients with lower risk of hypertension and deletions that include the NCF1 locus." (PMID 22319452, 2012). "The fact that genetic reduction of ROS-producing mechanisms occurred in the DD/Ncf1+/− mice suggested that pharmacologic treatment to reduce ROS may also be helpful in treating DD mouse hypertension." (PMID 22319454, 2012). "As in the case of Eln+/− mice, hypertension of DD mice is related to elevated angII plasma levels, and we have also shown over-expression of several NOX-related genes (Ncf1, Ncf2, Nox2/Cybb and Nox4) and significantly increased oxidative stress in these mice." (PMID 22319452, 2012).